OPTN (optineurin)
Diseases named in the same sentence as OPTN in open-access papers (continued):
Sharing a sentence is not in itself a finding about the gene and the disease.
glaucoma (continued). "In this study, we detected elevated TNF levels in glaucoma patients and demonstrated that OPTN-E50K operates via RIP1 to regulate RGC death." (PMID 39448868, 2025). "Through linkage analysis, 23 loci and four genes (MYOC/TIGR, CYP1B1, OPTN, and WDR36) had already been associated with glaucoma in the past years." (PMID 38241218, 2024). "In 2002, studies highlighted a significant correlation between a mutation in the gene for optineurin (OPTN) and glaucoma development in patients." (PMID 38255979, 2024). "Three genes associated with glaucoma have been identified within these loci: myocilin/trabecular meshwork glucocorticoid response (TIGR) (GLC1A), optineurin (GLC1E), and WDR36 (GLC1G)." (PMID 39456800, 2024). "Glaucoma, especially its intricate variants, is linked to variants in genes like MYOC, OPTN, and TBK1." (PMID 39766826, 2024). "Those rare variants are located in CYP1B1, SIX6, CARD10, MFN1, OPTC, OPTN, and WDR36 glaucoma-related genes." (PMID 38241218, 2024). "Three genes associated with glaucoma have been identified within specific loci, including myocilin/TIGR (GLC1A), optineurin (GLC1E), and WDR36 (GLC1G)." (PMID 39456800, 2024). "After sequencing the coding region of OPTN in glaucoma patients in this study by Sanger sequencing, we used the reference panel to detect OPTN rare variants." (PMID 39669598, 2024). "Like NEMO, mutations in OPTN have been found in several human diseases, but OPTN-associated diseases are neurological diseases including ALS and glaucoma." (PMID 37890781, 2023). "Like NEMO, mutations in OPTN have been found in several human diseases, but the OPTN-associated diseases are neurological diseases including ALS and glaucoma." (PMID 37292615, 2023). "A 2-base pair insertion in OPTN (619-692insAG or 2 bpIsn-OPTN) is associated with both ALS and glaucoma." (PMID 36875699, 2023). "For example, mutations in Optineurin (OPTN) affect mitophagy and these have been linked to incidence of glaucoma." (PMID 35313950, 2022). "Genetic screens have implicated Optineurin (OPTN), which is also known as optic neuropathy inducing protein, in many neurodegenerative diseases including primary open-angle glaucoma." (PMID 35145504, 2022). "Rab8, one of the proteins identified by our proteomic analysis, is a small GTP-binding protein that is related to optineurin, a glaucoma gene)." (PMID 39021423, 2022). "So far, several GWAS studies of glaucoma have identified over 100 risk loci, including mutations in the CYP1B1, OPTN, and PLEKHA7 genes." (PMID 34834521, 2021). "Cellular inclusions of mutant OPTN are a hallmark of amyotrophic lateral sclerosis (ALS) and primary open-angle glaucoma (POAG)." (PMID 33685483, 2021). "OPTN is a receptor for PARKIN-mediated mitophagy pathway, and mutations of OPTN cause primary open-angle glaucoma (POAG)." (PMID 33168089, 2020). "OPTN and APOE, implicated in Open Angle Glaucoma, demonstrated class-specific foveal enrichment among RGCs and Müller glia, respectively." (PMID 32555229, 2020). "Previous genome-wide association studies identified over 10 genes associated with primary open-angle glaucoma, including myocilin (MYOC), optineurin (OPTN) and WD repeat domain 36 (WDR36)." (PMID 32953253, 2020). "Another glaucoma mutant, M98K, displayed enhanced interaction and co-localization with TfR, accompanied by decreased Tf uptake, similar to E50K optineurin." (PMID 29875767, 2018). "Although more than 15 loci have been identified for glaucoma till date, only five genes have been identified with the causative mutations which include the following: MYOC/TIGR, OPTN, ASB10, WDR36, and EFEMP1." (PMID 28707069, 2018). "Overexpression of either ALS (E478G) or glaucoma optineurin mutants (E50K) resulted in a motor neuron axonopathy in zebrafish embryos, thus linking optineurin mutations to disease relevant phenotypes in vivo." (PMID 29875767, 2018). "Dysfunctional optineurin is implicated in several neurodegenerative diseases, particularly ALS and glaucoma." (PMID 29875767, 2018).
glaucoma (continued). "The role of OPTN in mitophagy was established in studies, which show that mutations in OPTN are associated with amyotrophic lateral sclerosis (ALS) and glaucoma due to mitochondrial dysfunction." (PMID 30483501, 2018). "The glaucoma mutant E50K forms larger and more granular structures compared to wild-type optineurin, inducing severe Golgi fragmentation." (PMID 29875767, 2018). "To date, more than 15 loci have been identified for glaucoma, and the causative gene has been identified for 5 of these loci: GLC1A (MYOC/TIGR), GLC1E (OPTN), GLC1F (ASB10), GLC1G (WDR36), and GLC1H (EFEMP1)." (PMID 28150229, 2018). "Two OPTN mutants and three ANG mutants were used: OPTN E50K, found in glaucoma patients; OPTN E478G; ANG K17I; ANG K40I; and ANG P112L, found in ALS patients." (PMID 28596290, 2017). "The involvement of optineurin, encoded by the OPTN gene, in ALS pathogenesis was identified years after the gene had been implicated in primary open-angle glaucoma." (PMID 26973461, 2016). "TBK1 encodes a kinase that phosphorylates OPTN and stimulates autophagy and mutations in TBK1 or OPTN appear to cause glaucoma via dysregulation of autophagy." (PMID 27275741, 2016). "Optineurin (OPTN) mutations cause neurodegenerative diseases, including amyotrophic lateral sclerosis (ALS) and glaucoma." (PMID 27552911, 2016). "Expression studies showed that optineurin is not only found in nerve fibers and retinal ganglion cells, as expected for a glaucoma-candidate gene, but also in the RPE." (PMID 25939269, 2015). "Optineurin or the “optic neuropathy inducing” gene was discovered in 2002 to be a candidate gene of primary open-angle glaucoma (POAG), the most common form of glaucoma." (PMID 25943884, 2015). "Linkage analysis of large pedigrees with Mendelian forms of glaucoma has identified three genes that cause glaucoma (MYOC, OPTN, and TBK1)." (PMID 24883232, 2014). "Mutations in Optineurin have been associated with ALS, glaucoma, and Paget’s disease of bone in humans, but little is known about how these mutations contribute to disease." (PMID 25329564, 2014). "More than 20 genetic loci have been linked to primary open angle glaucoma (POAG), which is the major type of disease, but only a few genes have been identified, including MYOC, OPTN and WDR36." (PMID 24752605, 2014). "To answer this question, we examined the effect of H2O2 and TNFα on OPTN oligomerization, since such stimuli have been proven to be increased in glaucoma patients and in turn contribute to retinal ganglion cells apoptosis." (PMID 24983867, 2014). "Optineurin was originally identified as a gene responsible for primary open-angle glaucoma, a progressive blinding disease, where pathology is due to the loss of the retinal ganglion cells and damage to their axons that make up the optic nerve." (PMID 25329564, 2014). "TBK1 phosphorylates OPTN and glaucoma-causing mutations in OPTN have been shown to alter the interaction between TBK1 and OPTN." (PMID 24883232, 2014). "In 2002, the optineurin or “optic neuropathy inducing” gene was identified to be a candidate gene of primary open-angle glaucoma (POAG), the most common form of glaucoma, one of the leading causes of irreversible bilateral blindness worldwide." (PMID 24683533, 2014). "Myocilin (MYOC), Optineurin (OPTN), WD repeat domain 36 (WDR36) and CYP1B1 are well-established causative genes for various forms of glaucoma." (PMID 25054348, 2014). "Contrary to other known genes causing PCG (CYP1B1) or POAG (MYOC, OPTN, and WDR36), one can easily consider a plausible cellular and molecular basis for association between LTBP2 and the glaucoma phenotype." (PMID 23401661, 2013). "Optineurin protein might play a role in the protection of the optic nerve from tumor necrosis factor-mediated apoptosis, and mutations in optineurin could lead to loss of function of this protein, which could decrease the threshold for ganglion cell apoptosis in patients with glaucoma." (PMID 22509109, 2012).
glaucoma (continued). "Four genes, including trabecular meshwork inducible glucocorticoid response (MYOC), human dioxin-inducible cytochrome P450 (CYP1B1), optineurin (OPTN), and WD repeat domain 36 (WDR36), have been identified as glaucoma-associated genes." (PMID 22876119, 2012). "Sequence tags from many glaucoma-related genes, including myocilin, optineurin, and WD repeat domain 36, were identified." (PMID 21528004, 2011). "Studies of rare families have mapped the position of 14 POAG genes to small regions of the genome and glaucoma-causing genes have been discovered in two of these loci, myocilin (MYOC) and optineurin (OPTN)." (PMID 21321670, 2011). "We also included MYOC, OPTN, and NTE, because these genes had previously been implicated in glaucoma." (PMID 21655191, 2011). "To date, about 23 loci have been linked to different types of glaucoma, and four genes, myocilin (MYOC), optineurin (OPTN), cytochrome P450 1B1 (CYP1B1), and WD repeat domain 36 (WDR36), have been identified as glaucoma causing genes." (PMID 19668597, 2009). "Besides MYOC (myocilin), at least two Mendelian glaucoma genes, TBK1 (TANK-binding kinase 1) and OPTN (optineurin), encode proteins that directly regulate PINK1–PARKIN signaling and LC3 (microtubule-associated protein 1A/1B-light chain 3) recruitment." (PMID 41516357, 2026). "OPTN is one of the very few genes that have a large effect on glaucoma, and the mutations in OPTN that promote glaucoma but not those that promote Amyotrophic Lateral Sclerosis (ALS) act in a gain-of-function manner to promote more or dysregulated mitophagy." (PMID 40795095, 2025). "This suggests that the M98K OPTN polymorphism alone is not a causative factor for glaucoma pathogenesis." (PMID 40385286, 2025). "Intriguingly, none of the OPTN glaucoma variants influenced OPTN recruitment for mitophagy, suggesting a distinct disease mechanism." (PMID 40385286, 2025). "TBK1, OPTN, and ATXN2 variants all cause familial ALS but also glaucoma." (PMID 38658168, 2024). "Interestingly, an OPTN E50K mutation was identified in familial primary open-angle glaucoma that promotes stronger interactions with TBK1, which in turn triggers an accumulation of insoluble OPTN and constriction of the Golgi body." (PMID 38287189, 2024). "In addition, several transgenic mice were created based on already discovered mutations in glaucoma patients, e.g., mutations in the genes MYOC/GLC1A, OPTN/GLC1E, and the tryptophan-aspartic acid repeat domain 36 (GLC1G)." (PMID 37791268, 2023). "Moreover, a glaucoma-associated mutated OPTNE50K enhances its interaction with TBK1 but reduces autolysosomes, and polyubiquitin binding to OPTN is required for optimal activation of TBK1 and production of IFN-β." (PMID 37352355, 2023). "OPTN, TANK binding kinase 1 (TBK1), and Myocilin (MYOC) are genes linked to glaucoma." (PMID 36589756, 2022). "In addition, duplication of TBK1 can cause glaucoma, for the reason that increased transcription of TBK1 encodes a kinase that phosphorylates OPTN, which recruits LC3B and initiates autophagy." (PMID 36589756, 2022). "Inherited forms of glaucoma may be attributed to single gene mutations, like myocilin (MYOC) and optineurin (OPTN), however these cases are rare and tend to occur early in life." (PMID 33413217, 2021). "Several hypotheses about the role of OPTN in glaucoma have indicated a neuroprotective function and shown that mutations may lead to RGC loss through downregulation or dysfunction of this protein." (PMID 33953963, 2021). "The impact of glaucoma-associated OPTN mutants in this NF-κB negative feedback loop is currently not known." (PMID 33953963, 2021). "ALS-causing mutations in OPTN inhibit Parkin-dependent mitophagy, while glaucoma-causing mutations do not." (PMID 34201955, 2021).
glaucoma (continued). "OPTN has been also proposed to exert a protective role in glaucoma development; however, in a transgenic mouse model that overexpressed Optineurin, high levels of this protein in the lens and the retina failed to protect against transforming growth factor-β1–induced apoptosis." (PMID 32340220, 2020). "GAS7 may interact with other genes implicated in glaucoma pathogenesis such as MYOC, OPTN, WDR36, CAV1, nitric oxide synthase 2 (NOS2), forkhead box C1 (FOXC1), apolipoprotein E (APOE), amyloid precursor protein (APP), and clusterin (CLU)." (PMID 32545285, 2020). "Some inherited forms of primary open-angle glaucoma have been reported to be associated with expression of a specific variant or mutation in different genes such as sine oculis-related homeobox 6 (SIX6) or OPTINEURIN (OPTN)." (PMID 30294255, 2018). "Although OPTN is expressed in several tissues, glaucoma-associated mutants do not seem to induce any pathology/disorder in any other cells or tissues in humans except in the retina." (PMID 29951055, 2018). "Autoimmunity has been implicated in glaucoma but involvement of OPTN or its mutants in autoimmnity has not been explored." (PMID 29951055, 2018). "We have shown that expression of either wild-type or ALS-associated mutant optineurin (E478G and Q398X) induced ER stress in motor neuron-like cell lines (NSC-34), in contrast to the E50K glaucoma mutant, although this induction was significantly enhanced in the mutant expressing cells." (PMID 29875767, 2018). "Two glaucoma-associated mutants of OPTN, E50K and M98K, but not an amyotrophic lateral sclerosis-associated mutant, E478G, induced cell death selectively in 661W cells." (PMID 29203899, 2017). "A glaucoma-associated mutant of OPTN, E50K, induces significantly more cell death than wild type OPTN when expressed in RGC-5 cells but not in many other cell lines tested such as HeLa, COS-7, Neuro2a, IMR32, and SH-SY5Y31–34." (PMID 29203899, 2017). "NTG patients carrying OPTN mutations do not show any other pathology except glaucoma phenotype, although OPTN is expressed in many tissues." (PMID 29203899, 2017). "We observed that the two glaucoma-associated OPTN mutants, E50K and M98K, but not an ALS-associated mutant, E478G, induced cell death in these cells but not in another neuronal cell line, NSC34, used as a model for ALS." (PMID 29203899, 2017). "Expression of some other glaucoma-associated mutants of OPTN (H26D, H486R, T202R, E322K) did not induce more cell death than WT OPTN in 661W cells." (PMID 29203899, 2017). "This conclusion is supported by RGC-like property of selective induction of cell death by glaucoma-associated mutants of OPTN in these cells but not in other neuronal cells." (PMID 29203899, 2017). "Indeed, mutation E50K of optineurin, a critical regulator of antiviral signaling, promotes interaction with TBK1 and is associated with familial primary open-angle glaucoma." (PMID 27454487, 2016). "Thus, it appears that these two glaucoma-associated proteins, TBK1 and OPTN, regulate each other’s activity to induce autophagy mediated cell death signalling." (PMID 26376340, 2015). "The optineurin gene, OPTN, is one of the causative genes of primary open-angle glaucoma." (PMID 24983867, 2014). "Similar studies of OPTN-related glaucoma with transgenic mice are also underway." (PMID 24883232, 2014). "Mutations in OPTN are associated mainly with normal tension glaucoma, a subset of POAG, where intraocular pressure is within normal limits (10–20mm Hg) but retinal ganglion cell death is observed leading to glaucoma." (PMID 24752605, 2014). "Optineurin (OPTN) and myocilin (MYOC) are two genes linked to glaucoma." (PMID 25250333, 2014). "Likewise in glaucoma, common pathogenic mutations had been found in unaffected individuals suggesting an incomplete penetrance, such as the MYOC p.Thr377Met, OPTN p.Glu50Lys, and WDR36 p.Asp658Gly." (PMID 22815630, 2012).
glaucoma (continued). "Among the five known glaucoma-causing genes– MYOC (myocilin), CYP1B1 (cytochrome P450, family 1, subfamily B, polypeptide 1), OPTN (optineurin), WDR36 (WDR36), and LTBP2 (latent transforming growth factor beta binding protein 2)–all except WDR36 were identified in three of the studies." (PMID 22312193, 2012). "However, genes consistently implicated so far (MYOC, OPTN, WDR36) are relevant only in a limited number of families and explain a small proportion of the glaucoma cases in the general population." (PMID 22570627, 2012). "Four genes, trabecular meshwork inducible glucocorticoid response (MYOC/TIGR), human dioxin-inducible cytochrome P450 (CYP1B1), optineurin (OPTN), and WD repeat domain 36 (WDR36), have been identified as glaucoma-causing genes, with MYOC being the first identified POAG gene." (PMID 21655360, 2011). "Adult-onset chronic open angle glaucoma, the most common type of glaucoma, has also been reported to show strong evidence for genetic heterogeneity, and at least 11 genetic loci, along with 3 genes (myocilin, optineurin, and WD repeat domain 36 gene [WDR36]), have been identified." (PMID 21921986, 2011). "However, retinal ganglion cells are target cells of glaucoma, and optineurin is mainly located in the optic nerve." (PMID 22194658, 2011). "Most carriers of OPTN and MYOC mutations develop glaucoma and asymptomatic carriers are rare." (PMID 21321670, 2011). "Optineurin, mutated in certain glaucomas and amyotrophic lateral sclerosis, is also a negative regulator of NF-κB activation." (PMID 21408173, 2011). "Patients with mutations in optineurin, such as E50K, have glaucoma and are not affected in other tissues although optineurin is expressed ubiquitously." (PMID 20085643, 2010). "We have shown earlier that the E50K mutant of optineurin selectively induces the death of RGCs, and not of other cell lines tested, indicating that this mutation causes glaucoma by directly inducing the death of RGCs." (PMID 20085643, 2010). "Yet, the mechanistic involvement of OPTN in glaucoma pathogenesis remains elusive." (PMID 19754948, 2009). "In addition, we analysed genes that have been previously identified as candidate genes in glaucoma (OPTN, OPA1, CYP1B1)." (PMID 19754948, 2009). "The aim of the current study was a similar evaluation of PEG patients for the presence of mitochondrial abnormalities and nuclear gene mutations associated with various types of glaucoma (MYOC, OPTN, WDR36, and CYP1B1) and certain inherited optic neuropathies (OPA1 and OPA3)." (PMID 18246027, 2008). "Moreover, there is no comprehensive study published to date that assesses the roles of three known glaucoma-causing genes (CYP1B1, MYOC, and OPTN) in the same set of Indian POAG patients." (PMID 17563717, 2007). "Mutations in the CYP1B1, MYOC, OPTN, and WDR36 genes result in glaucoma." (PMID 17563717, 2007). "Case-controlled study of OPTN sequence variants in individuals with or without glaucoma in populations of different ancestral origins and evaluate previous OPTN reports." (PMID 17293779, 2007). "Mutation in MYOC and OPTN, the high penetrance glaucoma genes, is responsible for about 4% of POAG conditions globally whereas the remaining is likely attributed to a combination of both environmental and genetic factors contributing to the complex inheritance of glaucoma." (PMID 37962455, 2024). "However, in vitro studies in cells expressing mito-Keima, a reporter of mitophagy flux, reported no mitophagy defects in cells expressing several glaucoma-associated optineurin mutations." (PMID 37034386, 2023). "Among the genetic risks associated with glaucoma, the E50K mutation in the Optineurin (OPTN) gene are known to result in glaucoma in the absence of increased intraocular pressure (IOP), whereas the relevant pathological mechanism and neurological issues remain to be further investigated." (PMID 35436991, 2022).